Y_RNA (Y RNA )
Gene: Miscellaneous RNA gene on chromosome 20 (35,853,252 to 35,853,364, reverse strand). Ensembl gene ENSG00000199676.
Homologues: Orthologues: macaque Y_RNA (92% identical). Paralogues in human: RNY1 (88% identical), Y_RNA (85% identical), Y_RNA (84% identical), Y_RNA (83% identical), Y_RNA (82% identical), Y_RNA (81% identical), RNY1P7 (81% identical), RNY1P8 (80% identical), Y_RNA (80% identical), RNY1P11 (79% identical), Y_RNA (79% identical), Y_RNA (78% identical), and 99 more.